MMP9 (matrix metallopeptidase 9)
Diseases named in the same sentence as MMP9 in open-access papers (continued):
Sharing a sentence is not in itself a finding about the gene and the disease.
cancer (continued). "Together, these results confirm the contribution of MMP-2 and MMP-9 to cancer angiogenesis through the degradation of ECM components and the activation of pro-angiogenic factors VEGF and TGF-β in diverse cancer tissues." (PMID 31921634, 2019). "MMP9 and MMP2 are proteases in the MMP family, which, in TNBC tissues, are necessary for extracellular matrix remodeling and cancer cell invasion." (PMID 32047724, 2019). "Combination activity of MMP2, MMP9 and MMP14 is crucial in initiating localized degradation of the gelatin by invadopodia during cancer metastasis." (PMID 31323836, 2019). "Lectin, a glycoprotein isolated from the fruit sap of P. fistulosus, exhibits its potential role against cancer development by decreasing VEGF secretion and inhibiting the expression of MMP2 and MMP9." (PMID 30871059, 2019). "In contrast, the overexpression of UCA1 in DU-145 showed increased level of E-cadherin but decreased level of Vimentin, MMP-9 and N-cadherin (P<0.01), validating the aggressive role of UCA1 in cancer metastases." (PMID 30940776, 2019). "MMP is a type of extracellular proteolytic enzyme, which can degrade basal membrane and promote invasion and migration of malignant tumors, of which MMP-2 and MMP-9 are two primary enzymes to degrade type IV collagen." (PMID 31101062, 2019). "Following these morphological changes, the cancer cells become migratory and invasive due to an enhanced expression of matrix metallopeptidase 2 (MMP-2) and matrix metallopeptidase 9 (MMP-9)." (PMID 31216782, 2019). "We found that radiation induced the up-regulation of the chemokine CXCL12 and its receptor CXCR4, of the metalloproteinases 9 and 12 (MMP9 and MMP12), and of key transcription factors involved in the expression of genes related to migration of cancer cells." (PMID 30813636, 2019). "Several triple-evidenced genes (MMP9, MMP11, CXCL12, MYL9) appear in three out of the five significantly enriched pathways and in more than half of the 13 cancers." (PMID 30729033, 2019). "In ER-positive luminal cancer cells like MCF7 and T47D, secretory factors like MMP-9 promote invasive and migratory potential in cancer cells once they are cultured with macrophages." (PMID 31075939, 2019). "Of these proteases, MMPs such as MMP-9, MT1-MMP, and uPA are thought to play an important role in cancer invasion." (PMID 31540489, 2019). "Several proteins are closely related to the migration and invasion of cancers, such as VEGFA, MMP2, and MMP9." (PMID 31631580, 2019). "The lower plasma ratio in cancer patients is determined by the high TIMP-1 concentration and relatively low MMP-9 concentration in comparison to the control group." (PMID 31143300, 2019). "In short, the collaborative work of CCR1, MMP9, and MMP2 at metastatic sites promotes cancer metastasis." (PMID 31474975, 2019). "For improving the understanding of SEMA6A-derived migration pathway, we also determined the mRNA expression levels of PLAU, MMP1 and MMP9 using RT-qPCR, because these genes were indicated to be reduced by HMOX1 and to induce migration in cancer cells." (PMID 31527696, 2019). "At the other end of the linear subnetwork, there are MMP9 and SDC4, established mediators of cancer invasion and apoptosis." (PMID 30978274, 2019). "Matrix metalloproteinase-9 (MMP-9) is responsible for matrix degradation, cancer invasion and metastasis." (PMID 31831717, 2019). "Furthermore, we have selected few significant markers, such as survivin, Bcl-2, and MMP-9, for RT-PCR analysis that may represent important hallmarks of cancer, and the appearance of survivin, Bcl-2, and MMP-9 genes were substantially repressed upon FCN exposure." (PMID 31466313, 2019). "In agreement with our data, low-density lipoprotein receptor-related protein-1 (LRP-1) and ApoE-binding receptors promote cancer cell migration via induction of MMP-2 and MMP-9 expression, and are involved in inducing cyclin D1 in interstitial fibroblasts." (PMID 31275318, 2019).
cancer (continued). "As shown in this study, NAP1 functions to activate MMP9 in NSCLC cells, which profoundly advances the understanding of mechanisms of action in cancer metastasis." (PMID 30867003, 2019). "The results here reported demonstrate novel biological properties of LPE that are able to prevent IL-6-induced invasiveness, to reduced IL-6-stimulated MMP-9/2 up-regulation in gastric MKN-28 and AGS cancer cell lines, and to inhibit in vitro AChE activity." (PMID 31817563, 2019). "Activated CAFs further promote cancer progression via secreting angiogenic cytokines including VEGF, matrix metalloproteinase (MMP)-2, MMP9, basic fibroblast growth factor and transforming growth factor-β." (PMID 31998637, 2019). "MMP1, MMP9, MMP10, MMP11, and MMP13 were almost universally upregulated across all cancers, with significant (p < 0.05) fold change (FC > 2) in ten of fifteen cancers." (PMID 31200666, 2019). "Angiogenesis is a major target in cancer treatment and MMPIs have been developed against proangiogenic MMPs such as MMP8 and MMP9." (PMID 31514474, 2019). "MMP-9 is more well know in the MMPs family, which can degrade type IV collagen in ECM, allowing cancer cells to break through the basement membrane of the primary site." (PMID 31038586, 2019). "Phosphorylation induces the degradation of IκBα, increasing NFκB activity, which in turn augments matrix metalloproteinase 9 (MMP9) expression and initiates extracellular matrix (ECM) degradation with consequent cancer cell invasion." (PMID 29478325, 2019). "The following molecular mechanisms may be involved in the carcinogenesis of PTC: First MMP-9 is involved in the degradation of type IV collagen and denatured collagen (critical component of basement membrane), which contributes to the aggressiveness of carcinoma." (PMID 33817161, 2019). "It has been reported that poor prognosis in several patients with cancer correlates with the increased activity of MMP-2 and MMP-9." (PMID 30336548, 2018). "The expressions of VEGF-α, MMP2, MMP9, bFGF and TGF-β were all increased from CAFs of human HCC cancer cell lines compared with the normal HSCs." (PMID 30591064, 2018). "MMP-9, a major regulator inducing ECM component degradation, is highly expressed in many human cancer types compared with normal controls." (PMID 30237810, 2018). "This indicates that actein can upregulate the expression of inhibitors TIMP-1 and TIMP-2 but downregulate the expression of MMP-9 and MMP-2, thereby resulting in the suppression of cancer metastasis." (PMID 30618758, 2018). "eIF4E phosphorylation was previously suggested to control cancer metastasis, by controlling ECM function and in particular the translation of MMPs, such as MMP-9." (PMID 29367404, 2018). "DA exerts its anti-inflammatory effects by modulating the activation of MMP-9, PI3K, ERK, NFκB, and VEGF in cancer cells." (PMID 30060484, 2018). "Our recent study demonstrated that cancer cell migration and invasion is partly dependent on EMT process and matrix MMPs such as MMP2 and MMP9." (PMID 29300772, 2018). "Malignant ascites-released membrane vesicles contain diverse activated proteases including MMP2, MMP9, uPA and ADAM17/TACE, together promoting ECM degradation and enhancing cancer cell invasiveness and metastasis." (PMID 28929459, 2018). "In this report, CTHRC1 upregulation was associated with lymphatic metastasis, distant metastasis, and MMP7 and MMP9 overexpression in NSCLC patients, indicating CTHRC1 plays a critical role in promoting cancer invasiveness." (PMID 29631554, 2018). "To exclude the contribution of secretion of MMP-9 and MMP-2 from cancer cells, we established MMP-knockdown cells by the RNA interference procedure." (PMID 30544870, 2018). "Epoxyazadiradione also inhibits the important hallmarks of cancer such as cell proliferation, migration and angiogenesis that is probably due to inhibition of OPN, VEGF, Cox2 and MMP-9 expression and activation." (PMID 29310608, 2018).
cancer (continued). "Similar to cancer cell lines, but less dramatically, mf altered the mRNA expression of IL-1β, CCL13, TGM2 and MMP9." (PMID 29668679, 2018). "Studies have shown that the PI3K/AKT signaling pathway plays an important role in invasion and distant metastasis of cancer through MMP-2 and MMP-9 regulation." (PMID 29977159, 2018). "MMP-9 and MMP-2 are recognized as playing a vital role in cancer cell invasion and metastasis among the MMP family." (PMID 29565268, 2018). "In our study, the down-regulations of MMP-2, MMP-9, and Vimentin reflected the inhibitory effects of APS on migration and invasion of MG63 cells, suggesting that APS exerted anti-cancer role in OS also by inhibiting cell migration and invasion." (PMID 30462772, 2018). "MMP-2 and MMP-9 are known to be proteolytically activated by MT1-MMP and assist cancer cell invasion." (PMID 29507310, 2018). "Our results suggest that although some genes were commonly modulated (eg., MMP9 and PGAM1 were upregulated by both normal and cancer exosomes), the effects were significantly amplified by cancer exosomes in recipient cells." (PMID 30008265, 2018). "Here our data indicate that exposure of human monocytes to all three-cancer cell lines results in significant induction of VEGF and MMP9 suggesting a phenotype similar to TAMs." (PMID 29668679, 2018). "TA-1 inhibited the proliferation, invasion, and metastasis of Panc28, Miapaca, and HL60 cancer cells by down-regulating Bcl-xL, XIAP, survivin, MMP-9, and CXCR4 expression." (PMID 30190788, 2018). "IR increases the migration and invasion capabilities of human cancer cell lines derived from CRC, lung cancer and glioblastoma, together with the upregulation of MMPs such as MMP-2 and MMP-9." (PMID 30336548, 2018). "We found that IL-20 is able to stimulate the growth, migration, and function as an upstream mediator to enhance MMP-9, MMP-12, cathepsin K, and cathepsin G secretion in cancer cells." (PMID 29690863, 2018). "The matrix metalloproteinase-9 (MMP9) is most likely involved in the TNF-α-mediated fusion of human M13SV1-Cre breast epithelial cells and human MDA-MB-435-pFDR1 cancer cells." (PMID 29636110, 2018). "Studies have confirmed that many early-stage cancers express elevated levels of MMP-2, MMP-3, and MMP-9." (PMID 29390034, 2018). "We show that glucose starvation promotes cancer cell invasiveness and migration through LKB1-AMPK-regulated MMP-9 expression." (PMID 29973599, 2018). "Previous studies reported that MMP-12, MMP-9, and cathepsin K accelerate extracellular matrix (ECM) degradation leading the invasion and metastasis of cancer cells." (PMID 29690863, 2018). "We further investigated the effect of CASZ1 on the expression of several genes related to cancer cell proliferation and invasion, such as MMP2, MMP9, cyclinD1 and epithelial-mesenchymal transition (EMT) genes, which were controlled by the MAPK/ERK pathway." (PMID 29506567, 2018). "The activity of specific MMP types such as MMP-2, MMP-9 and membrane type 1 (MT1)-MMP is upregulated in most human cancers." (PMID 30208169, 2018). "MMP-9 degrades the collagen-rich ECM, which has been related to cancer invasiveness, metastasis, and recurrence." (PMID 30142200, 2018). "On the other hand, higher expression of HRAS, NRAS, APC, HFE, MMP9, and a high enrichment of MAPK/RAS, NFKB, and TNF signaling pathways are all evident in HLE cells as often seen in cancer." (PMID 30176945, 2018). "Our data suggest a new therapeutic potential to block cancer metastasis by targeting AR, EGFR and MMP-9 pathways in subsets of PCa patients." (PMID 30134822, 2018). "MMP2 and MMP9 are two important matrix proteinases in the MMP family that degrade type IV collagen, a major component of the basement membrane in cancers." (PMID 29849932, 2018). "Studies have shown that inhibition or reduction of VEGF, MMP2, MMP9, and CD31 activity leads to reduction of angiogenesis, invasion, and cancer cell metastasis." (PMID 30127820, 2018).
cancer (continued). "The MMP family represent an ideal group of targets to demonstrate our strategy because inhibiting MMPs is of clinical value, as both MMP9 and MMP14 are involved in cancer progression." (PMID 30174795, 2018). "And HuR interacts with the 3′ UTR of matrix metalloproteinase 9 (MMP-9), urokinase plasminogen activator (uPA) and its cell surface receptor uPAR to increase cancer invasion ability." (PMID 29728635, 2018). "Activated CAFs further promoted cancer progression by secreting angiogenic cytokines, including VEGF, MMP2, MMP9, bFGF and TGF-β." (PMID 30591064, 2018). "On the other hand, both qPCR and western blot assays confirmed that NKILA suppressed activation of several NF-κB target genes including CCND1, TWIST1, MMP9 and XIAP, all of which play vital roles in cancer growth and metastasis." (PMID 29348395, 2018). "For MMP9 and PGAM1, both normal (OK113) and cancer (SqCC/Y1) exosomes triggered dose-dependent upregulation of MMP9 and PGAM1, but cancer exosomes were significantly more potent than normal exosomes." (PMID 30008265, 2018). "Recent findings indicated that several proteases, including MMP-2, MMP-3, MMP-9, presenilin 1, and CD26, are promoters and mediators of EMT processes in different cancer types." (PMID 30134935, 2018). "At molecular level, cancer progression factors MMP2 and MMP9 are induced in response to RBP4 overexpression." (PMID 29642915, 2018). "Our previous studies on human carcinoma demonstrated that the EGCG+IIF combination was very effective in decreasing the expression of MMP-2 and MMP-9, which are molecular markers of invasion." (PMID 30135355, 2018). "More recently, OC-derived exosomes were reported to transfer CD44 into mesothelial cells, resulting in upregulation of matrix metalloproteinase 9 (MMP9) that, in turn, favoured cancer cell homing and invasion." (PMID 28320418, 2017). "To study this further, we analysed MMP9 secretion and activity in VCA nanobody expressing cancer cells." (PMID 28938008, 2017). "Meanwhile, the abnormal expression of MMP-9, MMP-2, vimentin and CD44v6 in cancer cells would lead to decreased adhesion, enhanced migration and invasion." (PMID 28774312, 2017). "MMP family members, especially MMP-2 and MMP-9, are known to digest collagen, gelatin and other components of the extracellular matrix (ECM), resulting in the breakdown of the barriers of cancer cells." (PMID 28729634, 2017). "The well-documented cancer-related genes NOTCH1, CDKN1A, EGR1, AKT3, TNF, MMP9, and SMARCA4 are located in the center of this newly constructed subnetwork." (PMID 28500316, 2017). "Cancer cells can also acquire an invasive capacity when EMT occurs, which upregulates the level of the invasion-related protein MMP-9 and the migration-related protein RAC1." (PMID 28404892, 2017). "The matrix metalloproteinases (MMPs), such as MMP-9 and MMP-2, play a critical role in cancer cell invasion and metastasis, which can degrade most components of the ECM." (PMID 28534824, 2017). "In particular, epithelial cancer cells have been shown to induce the production of MMP9 by stromal fibroblasts, leading to the remodelling of the ECM and TGFβ-driven cancer progression." (PMID 27586372, 2017). "Matrix metalloproteinases (MMPs), including MMP2, MMP9 and MTI-MMP (MMP14), are critical mediators within invadopodia that promote cancer cell invasion." (PMID 28436416, 2017). "Given the recent emphasis in the role of MMP-2 and MMP-9 in ECM degradation and cancer invasion we are focusing our studies on investigating MMP-2 and MMP-9 activity in Rb." (PMID 28633655, 2017). "MMP-9 is a downstream signaling molecule of CXCR4 and is critical for cancer cell migration and invasion." (PMID 28969005, 2017). "MMP-9 and ICAM-1 are critical to the invasion and metastasis of cancers, therefore serve as markers for assessing the invasiveness of our cellular model." (PMID 28903398, 2017).
cancer (continued). "A trend towards increased marker levels was observed with cancer progression, particularly for MMP-1 and MMP-9." (PMID 29207990, 2017). "Together, these results support the conclusion that daurinol mediated FAK inhibition is important in inhibiting cancer cell invasion and that MMP2, MMP9, and uPA expression is regulated by FAK in both MDA-MB-231 and A549 cancer cells." (PMID 28915654, 2017). "Hydration of the extracellular matrix (ECM) is an important process that allows cancer cell invasion and metastasis through the secretion of enzymes such as MMP‐2 and MMP‐9." (PMID 28846829, 2017). "Matrix metalloproteinases (MMPs) play an important role in cancer cell metastasis, as particularly observed for the roles MMP-2 and MMP-9 in the degradation of ECM." (PMID 28424406, 2017). "IIF also induced differentiation in several cancer cell lines, inhibited MMP-2 and MMP-9 and increased expression of their inhibitors (TIMP-1 and TIMP-2)." (PMID 28465354, 2017). "We next measured the effect of PA on mRNA and protein expression of MMP-2, MMP-9, TIMP-1, and TIMP-2 (which have critical roles in cancer cell migration and invasion) in HeLa cells by use of western blotting and RT-qPCR." (PMID 29267213, 2017). "Previous studies have shown that MMPs play an important role in cancer cell metastasis, with significant expression of MMP-2 and MMP-9 in A549 cells." (PMID 28424406, 2017). "We also observed a decrease in the mRNA expression of MMP9, a matrix metalloproteinase expressed in CRC31, and a reduction in the mRNA expression of the two established cancer stem cell (CSC) markers CD44 and LGR532,33." (PMID 29167573, 2017). "GRP78 promoted cancer metastasis via up-regulation of MMP-2 and MMP-9, the induction of epithelial-mesenchymal transition or activation of NRF-2/HO-1 pathway." (PMID 29069845, 2017). "Possibly, like in some other cancer cells, FN1 induced specific matrix metalloproteinases expression, such as MMP9/MMP2, to promote invasion and metastasis." (PMID 28147311, 2017). "Metastasis process involves invasion and migration of cancer cells and enzymes like MMP-2/MMP-9 play a major role in this process." (PMID 28724926, 2017). "All marker levels were found significantly different between healthy controls and cancer subjects (Mann-Whitney U test, P = 0.002 for EGF, sCD26, CAL, MMP-9, CEA and CYFRA 21.1; P = 0.018 for MMP-1 and MMP-7)." (PMID 28117344, 2017). "We have previously shown that MMP9 plays a protective role in CAC opposite to its conventional role of acute inflammation and cancer mediator." (PMID 29212256, 2017). "One of the major implications of MMPs in cancer progression is their role in ECM degradation, and MMP2 and MMP9 is capable of degrading type IV collagen." (PMID 29228607, 2017). "In particular, with enhanced PSC-derived Galectin-1 expression, Vimentin and MMP9 expression increased in the cytoplasm of the stromal area around the PDAC cells and E-cadherin expression decreased on the cancer cell membrane." (PMID 29156810, 2017). "MMP-2 and MMP-9 have been reported to play a critical role in cancer cell migration and invasion by contributing to the degradation of the ECM and cancer progression." (PMID 29267213, 2017). "Focal adhesion kinase (FAK) promotes secretion of MMP-9; conversely, inhibition of FAK reduces secretion of MMP-9 in carcinoma cells." (PMID 28969043, 2017). "The result showed that CD133+ cancer stem-like cells significantly exhibited the increased protein and mRNA levels of VE- cadherin, MMP-2 and MMP-9 (P < 0.05), compared with CD133− cells." (PMID 27074560, 2016). "Malignant cells produce proteolytic enzymes, including serine proteinase, cathepsins, metalloproteinases (MMPs), and heparanase, among which MMP-9 and MMP-2 play key roles in destroying the basement membrane for mediating cancer invasion and metastasis." (PMID 27391337, 2016). "The results indicated that B7-H3 had a close relationship with MMP9 and MMP2 expression in cancer cells." (PMID 27145365, 2016).